ACTA2 (actin alpha 2, smooth muscle)
Diseases named in the same sentence as ACTA2 in open-access papers (continued):
Sharing a sentence is not in itself a finding about the gene and the disease.
breast carcinoma (continued). "This set comprised senescence markers (CDKN1A, LMNB1, MKI67), apoptosis regulators (BCL2, BCL2L1), a highly overexpressed gene (ITGB6), and drug targets (ACTA2, GSDMC, KRT6A, PDE1A, PSMA8), all of which showed strong concordance with our RNA-seq data in all four breast cancer cell lines." (PMID 40312750, 2025). "Similarly, in breast cancer, podoplanin and S100A31, in colorectal cancer (CRC), ACTA2-TAGLN-PDGFA, and DCN-MMP2-COL1A213 have been used." (PMID 37626157, 2023). "Our previous analysis of open databases showed that ITGA11 expression was correlated positively with PDGFRB, ACTA2, TNC, COL1A1, and COL1A3 in human breast cancer, and the immunostainings showed that α11, PDGFRβ, and TNC were colocalized to CAF subsets in human breast cancer stroma." (PMID 36003785, 2022). "It was also demonstrated that induction of ACTA2 by EGFR and HER2 dimerization is regulated through a JAK2/STAT1 signaling pathway and that abnormal ACTA2 expression accelerates the invasiveness and metastasis of breast cancer cells." (PMID 34211976, 2021). "Indeed, a significant (P = 0.048, HR = 1.13 (1–1.28)) relationship between POU1F1/ACTA2 mRNA levels and RFS was found in a human breast cancer dataset (n = 3951 samples), which suggests a clinical prognostic value for both POU1F1 and α-SMA in breast tumors." (PMID 33714987, 2021). "In addition, levels of ACTA2 and STAT1 expression were highly expressed in HER2-positive breast cancers." (PMID 28881584, 2017). "ACTA2 and STAT1 expression was also increased in HER2-positive breast cancer patients." (PMID 28881584, 2017). "We found that expressions of alpha-smooth muscle actin (ACTA2) and signal transducer and activator of transcription 1 (STAT1) significantly increased with transient or stable overexpression of HER2 in EGFR-positive breast cancer cells." (PMID 28881584, 2017). "Finally, ACTA2 silencing completely suppressed cell migration and invasion in HER2-overexpressing breast cancer cells." (PMID 28881584, 2017). "Taken together, these results demonstrated that induction of ACTA2 by EGFR and HER2 dimerization was regulated through a JAK2/STAT1 signaling pathway, and aberrant ACTA2 expression accelerated the invasiveness and metastasis of breast cancer cells." (PMID 28881584, 2017). "The expression levels of FAP and ACTA2 in putative CAFs from breast tumors were higher than in fibroblasts from normal tissue, whereas CAV1 expression was lower in putative CAFs from breast carcinoma samples than in fibroblasts from normal tissues." (PMID 28596490, 2017). "We found that HER2 overexpression increases levels of ACTA2 and STAT1 in breast cancer cells." (PMID 28881584, 2017). "Acta2-Cre and Acta2-Cre–ERT can be used, but they will also drive recombination in smooth muscle cells and myoepithelial cells, which poses a particular challenge in mouse models of breast cancer, which has a high frequency of these cell types in the tumour microenvironment." (PMID 31980749, 2020). "However, the prognostic significance of ACTA2 expression in breast cancer patients has not been fully elucidated." (PMID 28881584, 2017).
thoracic aortic aneurysm (30 papers, 2009 to 2025). An aneurysm formed in the wall of the proximal portion of the descending aorta proceeding from the arch of the aorta. "Previous case reports indicated that the occurrence of thoracic aortic aneurysm or aortic dissection caused by mutations in the ACTA2 gene was age-related." (PMID 39267980, 2024). "Mutations in target genes of myocardin, including Myh11, Acta2, and Mylk, are known causes of thoracic aortic aneurysms with dissection (TAAD), but most studies show a limited genetic overlap between AAAs and TAAs." (PMID 37561588, 2023). "Another locus identified in this study, 10q22.1–22.2, contains the ACTA2 gene, of which pathogenic variants are the cause 14% of familial thoracic aortic aneurysms and dissection." (PMID 35228681, 2022). "The heterozygous mutations in ACTA2 lead to an inherited predisposition for thoracic aortic aneurysms and dissections (TAAD)." (PMID 32509885, 2020). "It is also known that BAV is more frequent in patients with thoracic aortic aneurysm (TAA) related to mutations in ACTA2, FBN1, and TGFBR2 genes." (PMID 28883797, 2017). "Mutations in ACTA2 are the most common genetic cause of thoracic aortic aneurysm, and are also the cause of other disorders, including Moyamoya disease, coronary artery disease and stroke as well as Multisystemic Smooth Muscle Dysfunction Syndrome." (PMID 29202781, 2017). "Acta2 encodes the single most abundant protein in vascular smooth muscle cells, and mutations in the human gene are associated with ascending thoracic aortic aneurysms and dissections." (PMID 19580648, 2009). "The ACTA2 variant is the main cause of familial thoracic aortic aneurysms and dissection." (PMID 39682617, 2024). "Thoracic aortic aneurysm is found in patients with ACTA2 pathogenic variants." (PMID 37298565, 2023). "The reported case shows that the recognition of characteristic cerebrovascular abnormalities such as a straight course of intracranial arteries can guide the detection of an ACTA2 variant and this in turn can lead to the detection of a thoracic aortic aneurysm." (PMID 37587538, 2023). "Additionally, mutated ACTA2 accounts for 12%–21% of familial thoracic aortic aneurysms/dissections, and the remaining identified genes represent only 1%–2% of individuals with nonsyndromic thoracic aortic aneurysms/dissections." (PMID 37183561, 2023). "The lifetime risk for an aortic event (defined as presentation with an acute aortic dissection or surgical repair of a thoracic aortic aneurysm) is 76%, suggesting that additional environmental or genetic factors play a role in expression of aortic disease in individuals with ACTA2 mutations." (PMID 35896809, 2023). "ACTA2 gene mutations in adults associated with thoracic aortic aneurysm and dissection (TAAD)." (PMID 36277748, 2022). "Familial thoracic aortic aneurysms and dissections (FTAAD), linked to mutations in genes like ACTA2 and MYH11, highlight the genetic heterogeneity of aortopathies." (PMID 40110250, 2025). "Mutations in genes such as NOTCH1, GATA5, and ACTA2 have been implicated in the pathogenesis of both BAV and thoracic aortic aneurysms, suggesting shared genetic etiologies." (PMID 40110250, 2025). "Thoracic aortic aneurysms in ACTA2 carriers are typically fusiform and initially involve the aortic root, extending into the ascending aorta and aortic arch." (PMID 35896809, 2023). "Although thoracic aortic aneurysm and/or dissection is the main clinical manifestation, a variety of occlusive vascular disease and extravascular manifestations occur in ACTA2-related vasculopathy." (PMID 31752940, 2019). "In a large BAV/TAA cohort, SMAD6 variants were specifically enriched among patients with concurrent thoracic aortic aneurysms, while NOTCH1 and ACTA2 mutations were also documented in familial or heritable forms of aortic valve disease and aortic wall pathology." (PMID 41002609, 2025).
thoracic aortic aneurysm (continued). "Multiple genes can determine a familial pattern of thoracic aortic aneurysms, most of them having autosomal dominant inheritance, with the highest studied and prominently featured in the academic field being ACTA2, MYH11, MYLK, PRKG1, and those involved in the TGF-β pathway." (PMID 39685614, 2024). "Additionally, our studies found decreased integrin recruitment at cell-matrix adhesions in Acta2−/− mice which leads to a decreased ability for mechanosensing and further reduces contractility, leading to thoracic aortic aneurysm and dissection (TAAD)." (PMID 37298565, 2023). "Thoracic aortic aneurysms and dissections (TAAD), occlusive vascular diseases such as juvenile strokes and coronary artery disease (CAD) are the most common and clinically relevant vascular manifestations of ACTA2 variants." (PMID 37587538, 2023). "Interestingly, Acta2 was previously reported to contribute to AngII-induced thoracic aortic aneurysms (TAA) and dissections." (PMID 33195484, 2020). "However, vascular smooth muscle disease has also been attributed to mutations in actin and myosin genes with the discovery of mutations in ACTA2 and MYH11 in thoracic aortic aneurysms and dissections." (PMID 24676022, 2014). "Previous studies suggested that mutations in ACTA2, the gene encoding a-SMA, are the most frequent cause of non-syndromic, heritable thoracic aortic aneurysms and dissection." (PMID 39744109, 2024).
renal fibrosis (21 papers, 2017 to 2026). A final common manifestation of a wide variety of chronic kidney diseases characterized by glomerulosclerosis and tubulointerstitial fibrosis. "HY7718 supplementation was associated with reduced expression of genes related to renal fibrosis (Col1a1, Acta2) and vascular inflammation (Icam-1, Vcam-1)." (PMID 42196327, 2026). "In our study, exposure to TAC caused fibrotic changes and significant increases in Acta2, a biomarker of renal fibrosis, and Kim-1, a biomarker of renal injury." (PMID 38540134, 2024). "Acta2 encodes α-smooth muscle actin, a marker of activated myofibroblasts, which increase in number in renal fibrosis and secrete excess extracellular matrix components." (PMID 31803059, 2019). "Confirming our dose range experiments, X203 reduced AKI-induced loss of kidney mass, limited renal fibrosis, and improved renal function while lowering inflammatory (Tnfα, Il6, Ccl2, Ccl5, Il1β), fibrosis (Col1a1, Col1a2, Col3a1, Fn1, Acta2) and tubular damage (Kim1, Ngal) markers." (PMID 36470928, 2022). "Particularly, the elevated expression of ACTA2 indicates a potential pivotal role of myofibroblast activation in driving heat‐induced renal fibrosis." (PMID 41573374, 2026). "LIPUS drastically downregulated the mRNA levels of renal fibrosis markers, such as Tgfb1, Serpine1, Fn1, and Acta2." (PMID 40729113, 2025). "MDK mainly expressed by CD31+ACTA2+ ECs during partial EndMT contributes greatly to myofibroblasts and promotes renal fibrosis through stabilizing C/EBPβ, which subsequently activate ACTA2 expression by directly targeting its promoter region." (PMID 38714800, 2024). "The renal fibrosis amelioration was confirmed by the reduction in mRNA levels of Acta2, Collagen I, Collagen III, Mmp2, and Mmp9 and the protein levels of ACTA2, fibronectin, and Collagen I in UI30/2wk Pfkfb3f/f/PostnMCM kidneys compared to PostnMCM kidneys." (PMID 37626891, 2023). "During renal fibrosis, myofibroblasts express α-smooth muscle actin (Acta2), and TGF-β1 transgenic kidneys overexpressed Acta2 by 2-fold as compared to controls." (PMID 31277592, 2019). "Acta2, a gene encoded ⍺SMA, was also found to elevate early in the development of hypertension and was reduced after macrophage depletion, indicating the early onset of renal fibrosis in hypertension and that macrophage depletion reversed renal fibrosis." (PMID 41175639, 2025). "However, mice that underwent IRI displayed marked renal fibrosis compared with the sham controls, with a significant increase in staining for fibronectin, collagen IV, and Acta2 in myofibroblasts." (PMID 38625739, 2024). "In contrast to the findings with Insig1ΔKap mice, fibroblast deficiency of Insig1 did not worsen UUO-induced renal fibrosis, as evidenced by unchanged collagen deposition and fibrotic indicator (Fn, Acta2, Col3a1, and Vim) mRNA expressions in the kidneys." (PMID 38806641, 2024). "Conclusively, we proved that MDK increasingly expressed by CD31+ACTA2+ ECs during EndMT may be involved in the development of renal fibrosis." (PMID 38714800, 2024). "Recent studies have shown that adipose-derived stem cells are able to inhibit mRNA expression levels of COL1A1, transforming growth factor β1, connective tissue growth factor and alpha actin 2 (ACTA2) in renal fibrosis tissues, thereby playing a therapeutic role in renal fibrosis." (PMID 34359971, 2021). "(A) Decreased expression of HIST1H1B, a histone protein (B) increased expression of ACTA2, a marker of renal fibrosis, (C) decreased expression of NCLN, a part of the endoplasmic reticulum, and (D) decreased expression of CISD2, which is involved in mitochondrial autophagy." (PMID 33687326, 2021). "Thus, subsequent experiments used Cf48 LNA1 plus LNA2 (referred to hereafter as Cf48 LNA), which produced a substantial reduction in renal fibrosis as shown by Western blotting for collagen I and Acta2, and collagen deposition based on Masson’s trichrome staining." (PMID 38625739, 2024).
renal fibrosis (continued). "However, renal fibrosis is a stochastic process, with biopsies showing varying degrees of active and inactive fibrosis, with active fibrotic lesions identified by the presence of Acta2+ myofibroblasts." (PMID 38625739, 2024). "This study focuses on how endothelial cells contribute to ECM accumulation of renal fibrosis and suggests that MDK promotes ACTA2 expression by stabilizing the C/EBPβ protein." (PMID 38714800, 2024). "In accordance with this study, recent studies have also found that ADSC treatment significantly reduces renal fibrosis and reduces renal levels of mRNA COL1A1, TGFB1, CTGF, and ACTA2." (PMID 39309193, 2024). "Altogether, our study substantiates the involvement of MDK in mediating TGF-β-induced EndMT and renal fibrosis through stabilizing C/EBPβ, which is physiologically significant for emergence of CD31+ACTA2+ECs." (PMID 38714800, 2024). "The expression of renal fibrosis markers could potentially be affected by BMP signaling, but levels of Acta2 (α-smooth muscle actin), Col1a1 and Col3a1 (type I and III collagen α1 chains), Tgfb (TGF-β1), and Fn1 (fibronectin) were not significantly changed." (PMID 40773297, 2025). "A significant reduction in renal fibrosis in KO versus WT mice on day 28 of FAN was evident based on Masson’s trichrome staining, Western blotting for collagen I and Acta2, and immunofluorescent staining for collagen IV, Acta2, and fibronectin." (PMID 38625739, 2024). "Next, renal fibrosis markers were assessed, including COL1A1, VIM, CDH1, and ACTA2." (PMID 32854194, 2020). "Moreover, RNA-seq analysis revealed that the SVF-treated group exhibited significantly reduced expression levels of Fn1, Col1a2, and Acta2, suggesting that SVF may attenuate renal fibrosis progression." (PMID 40432888, 2025).
aneurysm (20 papers, 2009 to 2025). Bulging or ballooning in an area of an artery secondary to arterial wall weakening. "Proteins such as MYH11 and ACTA2, known for their involvement in smooth muscle contraction and structural stability, have been implicated in aneurysm pathogenesis through their influence on vascular smooth muscle cell (VSMC) function." (PMID 40881324, 2025). "Increased expression of Acta2 and other genes encoding smooth muscle cell proteins (Cald1, Dstn), in aortas protected from aneurysm, highlight the importance of vascular smooth muscle cells in maintaining vascular integrity." (PMID 19580648, 2009). "However, Angiotensin II infusion of Acta2−/− mice did result in enhanced dilation of the thoracic aorta, demonstrating that deficiency of ACTA2 promotes aneurysm formation in combination with chemical induction." (PMID 35492343, 2022). "Three patients were found to have Marfan syndrome, one patient had Loeyz-Dietz syndrome, one patient had an alpha smooth muscle actin (ACTA2) mutation and one patient showed a suspected congenital disorder because of various aneurysms in the patient’s medical history." (PMID 34934131, 2021). "The pathogenic variant ACTA2 c.536G>A (p.R179H) causes multisystemic smooth muscle dysfunction syndrome, a severe disorder marked by widespread smooth muscle abnormalities, resulting in life-threatening aortic disease and high risk of early death from aneurysms or stroke." (PMID 40378078, 2025). "Genetic factors also play an important role, such as ACTA2 mutations that affect smooth muscle actin and MYH11 mutations that alter smooth muscle contractile proteins, increasing the risk of aneurysms." (PMID 40176978, 2025). "The cerebral arterial pathology was quite variable and included aneurysms, moyamoya changes, and arterial stenosis, occlusion, and straightening; the latter is similar to the ACTA2 “broomstick arteriopathy”." (PMID 41040781, 2025). "The same is likely true of more recently described aortopathies such as AOS and ACTA2 related aneurysms and smooth muscle cell dysfunction." (PMID 36312254, 2022). "Despite the hypotension, Acta2−/− mice develop aortic root and ascending aneurysms by 6 months of age, and increasing blood pressure significantly accelerated enlargement of the aortic root and ascending aorta." (PMID 34600884, 2021). "Losartan, an angiotensin II receptor blocking agent, attenuated aneurysm formation, supporting that signaling through the angiotensin II receptor type Ia was in part responsible for thoracic aneurysm formation in the Acta2−/− mice." (PMID 34600884, 2021). "Further analysis showed decreased SM α-actin+ area and mRNA expression levels of Acta2 and Col1a1 genes in aneurysms from Apoe−/−Light−/− mice, which are compatible with the loss of VSMC contractile phenotype." (PMID 34829747, 2021). "Acta2 (vascular smooth muscle actin) expression was increased in aortas resistant to aneurysm formation compared to other groups." (PMID 19580648, 2009). "In addition, aneurysm tissue showed an altered collagen structure and decreased levels of fibrillin and ACTA2." (PMID 38636100, 2024). "Comparing smooth muscle cell markers such as Acta2, Tagln, Myl9, Myl6, Cnn1, and Myh11, these markers were expressed less in thoracic aneurysm SMCs, suggesting a less-differentiated state of the thoracic aneurysm SMCs." (PMID 39590192, 2024). "MKL1 protein staining was much stronger in AAA lesions compared with control non-aneurysm aortic tissues, whereas ACTA2, a SMC marker protein, was reciprocally expressed in those tissues, indicating that VSMC phenotypic switching occurs during AAA formation in humans." (PMID 33667992, 2021). "Age at diagnosis differed between groups: Marfan = 22.0 ± 16.6; Loeys-Dietz = 29.6 ± 21.5; aneurysm-osteoarthritis = 36.4 ± 18.8; ACTA2 aneurysm = 43.4 ± 18.6; non-syndromal heritable aortopathy = 47.2 ± 16.6 years (p < 0.001)." (PMID 36312254, 2022).
aneurysm (continued). "Surprisingly, mouse models have shown that simply deleting ACTA2 does not lead to aneurysm; aneurysms developed only upon exposure to angiotensin II, indicating an interplay between genetics and environmental factors in the development of TAAD." (PMID 31991693, 2020). "Human aortic samples were collected from MFS and non-MFS aneurysm patients to study complement factor gene expression C1R, C1S, C3AR1, and C5AR1 and SMC gene ACTA2." (PMID 36279189, 2022).